SUGCT (succinyl-CoA:glutarate-CoA transferase)
Description:
Coenzyme A (CoA) transferase that reversibly catalyzes the transfer of a CoA moiety from a dicarboxyl-CoA to a dicarboxylate in a metabolite recycling process. Displays preference for succinyl-CoA and glutarate-CoA as dicarboxyl-CoA donors and glutarate, succinate, adipate/hexanedioate, itaconate and 3-hydroxy-3-methylglutarate as dicarboxylate acceptors. Acts on intermediates or end products of lysine and tryptophan degradation pathway, in particular catalyzes succinyl-CoA-dependent reesterification of free glutarate into glutaryl-CoA to prevent renal excretion of glutarate. Upon inflammation, may convert macrophage-derived itaconate to itaconyl-CoA in erythroid precursors where it negatively regulates the TCA cycle and heme synthesis to limit erythroid differentiation in the context of stress erythropoiesis.
Synonyms: C7orf10; DERP13; FLJ11808; ORF19; GA3
Tractability: Small molecule: a structure with a bound ligand is known. PROTAC: ubiquitination databases record sites on it; its protein half-life has been measured.
Safety:
Unwanted effects reported when the protein is acted on. In parentheses: how it was acted on, where the effect was seen, and who reports it.
venous thrombosis (source: ClinPGx)
Gene: Protein-coding gene on chromosome 7 (40,134,044 to 40,861,613, forward strand). Ensembl gene ENSG00000175600.
Subcellular location: Mitochondrion
Subcellular location (Human Protein Atlas): Microtubules; Primary cilium; Basal body; Mitotic spindle
Gene Ontology:
Molecular function: succinate-hydroxymethylglutarate CoA-transferase activity; catalytic activity
Cellular component: mitochondrion
Genetic constraint (gnomAD): Loss-of-function variants: 23 observed, 28.46 expected, observed/expected ratio (o/e) 0.81, 90% interval 0.58 to 1.14. The upper end of that interval is the gene's LOEUF score, 1.14, which puts it in group 5 of 6, group 1 being the genes least tolerant of losing a copy. Missense variants: 376 observed, 352.37 expected, observed/expected ratio (o/e) 1.07, 90% interval 0.98 to 1.16. Synonymous variants: 133 observed, 133.16 expected, observed/expected ratio (o/e) 1, 90% interval 0.87 to 1.15.
Gene-disease validity (ClinGen):
ClinGen rates the evidence that SUGCT causes each of these diseases.
glutaric acidemia type 3 (autosomal recessive): Moderate. Glutaryl-CoA oxidase deficiency is a peroxisomal disorder leading to glutaric aciduria.
Homologues: Orthologues: chimpanzee SUGCT (99% identical), macaque SUGCT (97% identical), rabbit SUGCT (91% identical), pig SUGCT (89% identical), dog SUGCT (88% identical), mouse Sugct (84% identical), rat Sugct (81% identical), guinea pig SUGCT (76% identical), tropical clawed frog sugct (70% identical), Drosophila melanogaster CG10877 (45% identical), zebrafish sugct (38% identical). Paralogues in human: AMACR (23% identical).
Diseases named in the same sentence as SUGCT in open-access papers:
SUGCT is named in the same sentence as 31 diseases in open-access papers, as found by Europe PMC text mining. Sharing a sentence is not in itself a finding about the gene and the disease. The quoted sentences say what the papers report.
glutaric aciduria type 3 (4 papers, 2018 to 2022). "Independent variants in the SUGCT gene have been associated with glutaric aciduria type 3 disease susceptibility." (PMID 36064556, 2022). "SUGCT (succinyl-CoA: glutarate-CoA transferase) was demonstrated to be related to mitochondrial diseases and glutaric aciduria type III that might play a role in hepatic energetic metabolism." (PMID 30243023, 2018).
migraine (4 papers, 2017 to 2021). "Unadjusted analyses showed that two SNPs were associated with migraine at a Bonferroni corrected threshold of 0.0013 (0.05/40): rs4814864, located in the SLC24A3 gene (OR = 1.32, p = 0.0008), and rs186166891, located in the SUGCT gene (OR = 1.48, p = 0.0004)." (PMID 28656458, 2017).
cancer (1 paper, 2023). A tumor composed of atypical neoplastic, often pleomorphic cells that invade other tissues. "Both the ADCY2 and SUGCT genes are involved in cellular metabolism and are reported to be altered in cancer." (PMID 38137002, 2023).
SUGCT also shares sentences with these, for which no sentence is quoted: infection (30 papers); virus infection (3); tumor (2); acne (1); bacterial infection (1); Bardet-Biedl syndrome (1); breast carcinoma (1); cadmium poisoning (1); cardiovascular diseases (1); COVID-19 (1); diabetes (1); diaphanospondylodysostosis (1); Ehlers-Danlos syndrome (1); Fanconi anemia (1); Hepatic steatosis (1); hepatocellular carcinoma (1); Infertility (1); latent infection (1); metabolic syndrome (1); Miscarriage (1); mitochondrial disease (1); nematode infection (1); oral candidiasis (1); ovarian carcinoma (1); primary ciliary dyskinesia (1); prostate carcinoma (1); Pyle disease (1); staphylococcal infection (1).